BRAF (B-Raf proto-oncogene, serine/threonine kinase)
Diseases named in the same sentence as BRAF in open-access papers (continued):
Sharing a sentence is not in itself a finding about the gene and the disease.
metastatic melanoma (continued). "In conclusion, we demonstrated that the detection of the BRAF and NRAS cfDNA status with the IdyllaTM assay is feasible in a routine manner in a pathology laboratory, before and after systemic treatment of patients with metastatic melanoma." (PMID 30546839, 2018). "We next performed immunohistochemical analysis of biopsies from 54 patients with genetically diverse metastatic melanoma and confirmed high expression of BRD4 in NRASMut tumors; BRD4 levels were markedly higher than in tumors harboring mutant BRAF or wild‐type for BRAF and NRAS (WT)." (PMID 29650805, 2018). "Furthermore, the recent development of potent highly selective BRAF and MEK inhibitors with unique pharmacologic profiles, has led to the potential for improved survival of patients with locally advanced or metastatic melanoma." (PMID 29100459, 2017). "According to metastatic melanoma french recommendations, the patient received vemurafenib (anti-BRAF) as a first line therapy without developing any significant side effects." (PMID 29195497, 2017). "After the introduction of these revolutionary therapies the BRAF inhibitor dabrafenib, MEK-inhibitors trametinib and cobimetinib, and the anti-PD1 antibodies nivolumab and pembrolizumab were approved for the treatment of metastatic melanoma." (PMID 28915798, 2017). "The introduction of targeted therapies including BRAF and MEK inhibitors as well as CTLA-4 and PD-1 axis targeting immune checkpoint inhibitors have dramatically improved the treatment and prognosis of patients with extracranial metastatic melanoma." (PMID 28374234, 2017). "A major limitation of our study is, however, the small sample size that cannot definitively establish the true benefit of this approach in patients with wild-type BRAF metastatic melanoma who are not eligible or non-responsive to new immunotherapeutic drugs." (PMID 29120401, 2017). "There is evidence for a broad spectrum of genomic and non-genomic mechanisms of acquired resistance to BRAF inhibitors in metastatic melanoma." (PMID 28147313, 2017). "The use of nivolumab in combination with ipilimumab for the treatment of advanced melanoma patients with or without BRAF V600 wild-type metastatic melanoma has also been approved." (PMID 29033936, 2017). "In line, combination of BRAF and MEK inhibition, which inhibits the downstream activated MAPK pathways from different sites, resulted in a significantly prolonged progression free survival in extracranial metastatic melanoma." (PMID 28374234, 2017). "In metastatic melanoma, for example, the cooperation of CD8+ T cells and Natural Killer cells are necessary to mediate anti-tumor activity during combination therapy with IL2 and anti-CTLA, and for the use of BRAF inhibitors in metastatic melanoma." (PMID 27377892, 2016). "Therefore, a combination of BRAF inhibitor (dabrafenib) and MEK1/2 inhibitor (trametinib) was approved in early 2014 for the treatment of metastatic melanoma, to which incidences of resistance has already been observed." (PMID 26497853, 2015). "Pembrolizumab is a programmed death receptor-1 (PD-1) blocking antibody approved for the treatment of metastatic melanoma that has progressed past cytotoxic T-lymphocyte antigen 4 (CTLA-4) inhibitor Ipilimumab and BRAF inhibitors such as vemurafenib or dabrafenib (if BRAF mutated)." (PMID 26448890, 2015). "It is highly likely that acquired resistance to the increasing use of dual BRAF and MEK inhibition for the upfront treatment of patients with metastatic melanoma may lead to increased reliance on MAPK-independent pathways during drug escape." (PMID 24735930, 2014). "Ipilimumab has been shown to improve overall survival in approximately 80% of patients with metastatic melanoma who have not received prior therapy with BRAF inhibitors." (PMID 23497384, 2013).
metastatic melanoma (continued). "This is currently happening in metastatic melanoma, where recent experience has indicated that around half of patients receiving BRAF inhibitors do not gain the same benefit from subsequent treatment with ipilimumab as BRAF inhibitor treatment-naïve patients." (PMID 23497384, 2013). "BRAF inhibition has a documented survival advantage in metastatic melanoma without brain metastases." (PMID 24403263, 2013). "By contrast, ipilimumab can be used to treat patients with metastatic melanoma, regardless of their BRAF status." (PMID 22640478, 2012). "However, patients with BRAFV600E mutant cutaneous metastatic melanoma enrolled in clinical trials testing MEK inhibitors have lower response rates than the use of the type I BRAF inhibitors vemurafenib or dabrafenib (GSK2118436) in the same population." (PMID 22515704, 2012). "Two large phase-III trials of sorafenib in combination with carboplatin/paclitaxel in chemotherapy-naive and pre-treated patients with BRAF undefined metastatic melanoma did not meet the primary endpoint of improved overall survival." (PMID 21139585, 2011). "In February 2024, the FDA granted accelerated approval to lifileucel, a TIL-derived autologous T-cell therapy, for unresectable or metastatic melanoma previously treated with a PD-1 inhibitor and, if BRAF V600-positive, a BRAF inhibitor with or without a MEK inhibitor." (PMID 40576713, 2025). "In addition, BRAF inhibitors and ICI were both approved by the FDA for metastatic melanoma in 2011." (PMID 40362630, 2025). "Similarly, in another study, baseline NLR was a prognostic factor for PFS in patients with BRAF mutant metastatic melanoma, regardless of the therapy received, but only in univariate analysis." (PMID 39272837, 2024). "Differently from the treatment of the metastatic melanoma, where the ratio between risks and benefits of immunotherapy with ICI is in favor of the benefits, at least in the presence of BRAF wildtype tumors, the same risks/benefits balance could be completely altered in the adjuvant setting." (PMID 39148899, 2024). "Results showed the highest SNAI1 mRNA expression in metastatic melanoma, regardless of BRAF status." (PMID 39273022, 2024). "A CT-guided biopsy was completed which surprisingly revealed metastatic melanoma (BRAF-negative)." (PMID 39119371, 2024). "The strength of our study is that it used logistic regression models, and with the analysis we were able to identify independent prognostic factors that have not yet been described in relation to metastatic melanoma treated with BRAF + MEK inhibitors, which are worthy of further investigation." (PMID 39272837, 2024). "Potent and specific inhibitors of MAPK pathway mediators have been discovered and include BRAF inhibitors, e.g., vemurafenib or encorafenib, and MEK inhibitors, e.g., trametinib, which are FDA- and EMA-approved drugs that have been used alone or in combination regimes against metastatic melanoma." (PMID 36838864, 2023). "Furthermore, combining a BRAF inhibitor with a MEK inhibitor significantly improved OS in BRAF-mutant metastatic melanoma patients without an increase in overall toxicity." (PMID 37205993, 2023). "The expression of PD-L1 in tissue does not seem to be a good biomarker in metastatic melanoma treated with targeted therapy, although its expression does increase in the microenvironment after the inhibition of BRAF, both in preclinical models and in tumour biopsies." (PMID 35203494, 2022). "However, an additional MEK inhibitor that inhibits the MAPK pathway to BRAF inhibitors, trametinib, overcame BRAF inhibitor resistance, and demonstrated superiority over a BRAF inhibitor alone in phase III clinical trials in patients with BRAF mutant metastatic melanoma." (PMID 33673070, 2021).
metastatic melanoma (continued). "Although targeted therapy using BRAF/MEK inhibitors has dramatically changed the prognosis of patients with metastatic melanoma, patients with BM who received targeted therapy did not have a significant improvement in survival, with a median OS of 7–9.6 months." (PMID 33816300, 2021). "Combined BRAF and MEK inhibition has increased median patient free survival PFS, but patient overall survival could still be improved by preventing the emergence of drug resistance of late stage metastatic melanoma." (PMID 32708687, 2020). "Moreover, early clinical data in a small patient population suggests that targeted therapy with BRAF/MEK inhibitors may work in synergy with checkpoint inhibitors and this triplet therapy may improve survival in patients with metastatic melanoma." (PMID 32486190, 2020). "The ESMO-MCBS grade of CHECKMATE-066, which support the approval of nivolumab as first line therapy of BRAF wild-type unresectable or metastatic melanoma increased from 4 to 5 due to improved QOL, which were not available in the primary report and approval documents." (PMID 32867707, 2020). "This could also be an important factor affecting the results from the phase II clinical trial conducted using bortezomib for the treatment of metastatic melanoma, which demonstrated no clinical anti-tumor activity, since BRAF status was not taken into account." (PMID 27783987, 2016). "The use of anti-BRAF drugs (vemurafenib or dabrafenib) associated or not with anti-MEK therapy (trametinib or cobimetinib), has considerably improved progression-free and overall survival for patients bearing mutated V600 metastatic melanoma." (PMID 27111917, 2016). "A new paradigm for primary systemic treatment for metastatic melanoma has shifted toward immunotherapy including IL-2, anti-CTLA4 monoclonal antibody (ipilimumab), and programmed cell death 1 antibody (anti-PD1), as well as targeted therapies (BRAF or MEK inhibition)." (PMID 25932372, 2015). "For example, Vemurafenib (BRAF V600E inhibitor) and Ipilimumab (anti-CTLA4) were recently approved by the U.S. FDA and agents directed against the MAP kinase pathway (anti-MEK, anti-ERK, other anti-BRAF) are under development for targeted therapy in cases of advanced metastatic melanoma." (PMID 24499728, 2014). "Furthermore, frequencies of DCs, monocytes, T cells, B cells, NK cells, and regulatory T cells in peripheral blood from metastatic melanoma patients were not affected by BRAF inhibition." (PMID 24194739, 2013). "However, all these effects show a degree of heterogeneity when comparing different BRAF-mutant cell lines, suggesting that different metastatic melanoma lesions may not trigger the same arms of the immune response." (PMID 36726591, 2022). "Furthermore, the combination of the BRAF inhibitor, vemurafenib, and the MEK inhibitor, cobimetinib, also provided a significant benefit compared to vemurafenib alone, suggesting that dual targeting may provide better clinical outcomes for metastatic melanoma." (PMID 35048028, 2021). "However, chemotherapy is still utilized in metastatic melanoma, mainly in patients lacking a targetable mutation in the BRAF/MEK signaling pathway, or developing secondary resistance to BRAF/MEK inhibitors, and/or in patients not suitable or refractory to immune checkpoint inhibition." (PMID 29100289, 2017). "According to National Comprehensive Cancer Network (NCCN) guidelines, metastatic melanoma, irrespective of genotype status (BRAF or KIT mutations), can be treated with DTIC, temozolomide and paclitaxel, however, these treatments are not target-specific like BRAF and MEK inhibitors." (PMID 25742310, 2015).
metastatic melanoma (continued). "Most importantly, the absence of documentation of the examined molecular markers, such as BRAF, c-KIT, and CDK1, should not disorient readers from the importance of immunotherapeutic agents in metastatic melanoma." (PMID 39553047, 2024). "While trials testing different combination therapies are still ongoing, no one combination of BRAF and MEK inhibitors is clearly superior to the others for BRAF-mutant metastatic melanoma." (PMID 35453572, 2022). "One patient with in-transit metastatic melanoma, stage IIIB (patient No 1) received T-VEC after prior targeted therapy with BRAF/MEK inhibitor and obtained a long-lasting, complete response." (PMID 32052079, 2020).
thyroid cancer (876 papers, 2004 to 2026). "Recent studies have demonstrated that abnormal production of MMPs and inflammatory factors is a main mechanism by which BRAF mutations promote the pathogenesis of thyroid cancer, with TGF‐β1 playing a pivotal role in this process." (PMID 40620232, 2025). "Anaplastic thyroid cancer represents the most aggressive form of thyroid cancer and harbors BRAF mutations in over 40% of cases." (PMID 40063000, 2025). "We primarily aimed to determine the association of the Ki‐67 index and BRAF mutations with recurrent or persistent thyroid cancer." (PMID 40085528, 2025). "Our analysis of genetic alterations revealed a high prevalence of BRAF mutations, present in 58% of the thyroid cancer samples, with other genes showing mutations in 2% or fewer samples." (PMID 40450370, 2025). "We next evaluated the accumulation of total FAK in thyroid cancer cell lines expressing BRAF V600E mutations due to their association with recurrence, extrathyroidal extension, advanced stage, and distant metastases in thyroid cancer." (PMID 40458728, 2025). "Estrogen activates both genomic and non-genomic pathways linked to MAPK and PI3K signaling—the same pathways frequently mutated in thyroid cancer through BRAF, RAS, and RET alterations." (PMID 41595456, 2025). "Meanwhile, we also analyzed the expression levels of eight genes related to GPX4 and BRAF in thyroid cancer to further elucidate their association with thyroid ferroptosis and prognosis." (PMID 39917169, 2025). "Collectively, our data indicated that mannose improved the anti-tumor effect of PLX4032 in BRAF-mutated thyroid cancer cells." (PMID 40063000, 2025). "It contributes to the development of thyroid cancer, particularly papillary thyroid cancer, through genetic mutations such as BRAF mutations and enhanced cancer cell proliferation." (PMID 40241991, 2025). "Current research underscores the pivotal role of the RET and mutated BRAF genes in the progression and metastatic dissemination of thyroid cancer." (PMID 39917169, 2025). "Given the subnuclear punctate accumulation of pY397 FAK, we next aimed to investigate the accumulation of pY397 FAK in a panel of thyroid cancer cells with BRAF V600E and RAS mutations." (PMID 40458728, 2025). "Clinically, the presence of BRAF mutations in thyroid cancer has important implications for treatment strategies." (PMID 40450370, 2025). "Previous studies have shown that BRAF V600E-mutated thyroid cancers exhibit more aggressive behavior, and aspect ratio and ETE, as critical imaging features of PTC aggressiveness, are often closely associated with BRAF V600E mutations." (PMID 40900897, 2025). "Recently, the BRAF V600E mutation has become a commonly used biomarker for thyroid cancer recurrence." (PMID 40104288, 2025). "A meta-analysis of 29 studies, encompassing over 2000 thyroid cancer cases, reported an average BRAF mutation prevalence of 44% in PTC and 24% in ATC." (PMID 40363930, 2025). "The prevalence of BRAF V600E mutations in thyroid cancers in TCGA and AACR GENIE databases were (59% [n = 500] and 41% [n = 2769], respectively)." (PMID 40869231, 2025). "BRAF inhibitors, such as vemurafenib, encorafenib, or dabrafenib, have shown benefit in clinical trials in patients with thyroid cancer carrying the BRAFV600E mutation." (PMID 39744583, 2025). "PIK3CA is more typical of aggressive thyroid cancer types or advanced thyroid cancer, most commonly coexisting with BRAF mutation." (PMID 40226091, 2025). "As thyroid cancer care increasingly embraces precision medicine, future staging systems will likely integrate molecular markers (e.g., BRAF, RAS, TERT promoter mutations) with clinicopathological data." (PMID 41164799, 2025).